FOXP3 (forkhead box P3)
Diseases named in the same sentence as FOXP3 in open-access papers (continued):
Sharing a sentence is not in itself a finding about the gene and the disease.
tumor (continued). "Ever smoking, compared to never smoking, was associated with poorer CC-specific survival among individuals with lower densities of CD3+, CD4 +, and FOXP3 + tumour-infiltrating immune cells." (PMID 41631717, 2025). "The LOW group, when compared to the CIMP subset, showed the highest scores for CD3, CD4, CD8, FOXP3 and PD-1 in intra-tumor and extra-tumor compartments." (PMID 40682094, 2025). "On day 6 of tumor growth, there were more FoxP3+ Tregs eGFP+ signals in the tumor and peritumor space according to IVM data, but their share still did not exceed 5% of the total number of immune cells infiltrating the peritumor space." (PMID 40071070, 2025). "On one hand, its high expression can induce the abnormal accumulation of regulatory T cells (FoxP3+ T cells) in tumor tissues, creating an immunosuppressive microenvironment." (PMID 41445742, 2025). "On the other hand, we must consider the context-dependent functions of FOXP3+ Tregs, which not only support anti-tumor immunity but also contribute to maintaining the balance of immune responses in the TME." (PMID 39940924, 2025). "For instance, the abundance of exhausted T-cyt cells (CD8 + CD39 + PD-1 +) in ccRCC was found to be positively correlated with the abundance of T-regs (CD4 + FOXP3 +) and PD-L1 + tumor cells." (PMID 39751643, 2025). "These APCs display antigens in a way that promotes T cell exhaustion, inhibiting CTLs and promoting FOXP3+ Tregs, enhancing cancer cells’ survival and tumor metastasis." (PMID 39940924, 2025). "CD4+ T cells pre-activated with an anti-CD3 antibody and cultured with tumor cell-derived EVs induced a substantial expansion of CD4+CD25+ forkhead box P3 (FOXP3+) Tregs." (PMID 40182121, 2025). "In conclusion, high FOXP3‐positive cell density or FOXP3+/CD4+ cell ratio around the tumor correlated with a worse response to BCG treatment for bladder CIS." (PMID 40084633, 2025). "In HCC, the regulatory role of Tregs, influenced by FOXP3, can contribute to tumor progression by suppressing effective immune responses against cancer cells." (PMID 40438106, 2025). "We found that cytotoxic T cells (CD8+), regulatory T cells (FoxP3+) and macrophages have some prognostic relevance in the tumor near normal tissue and focused further on the presence of macrophages." (PMID 40498004, 2025). "Given that FOXP3 is a marker for Tregs, and considering the limited research on FOXP3 expression in EC tumor cells, the relationship between FOXP3 expression in these cells and patient prognosis warrants further investigation." (PMID 40587482, 2025). "The immune microenvironment, particularly CD4+ T-helper cells and FOXP3 (forkhead box P3)+ regulatory T cells (Tregs), plays a crucial role in tumor progression." (PMID 41007768, 2025). "Of note, OS was significantly shorter in the high IgG4 group, and Foxp3-positive cells in the tumor tissues were increased." (PMID 40563656, 2025). "CD8+LAG-3−PD-1+TIM-3−, CD4+PD-L1+, and CD4+FoxP3− T cell densities were significantly higher in the TLS within TC compared to tumour and stromal regions." (PMID 39901202, 2025). "As anticipated, radiation therapy resulted in an increase in the proportion of CD4 T cells that were CD25+FoxP3+ Treg and an overall increase in Treg as a proportion of live cells in the tumor." (PMID 41417245, 2025). "Regulatory T cells (Tregs), characterised by the expression of the master transcription factor forkhead box P3 (Foxp3), suppress anti-tumor immunity and obstruct effective anti-tumor immune responses in tumor-bearing hosts." (PMID 40356964, 2025). "The enhanced T cell effector responses suggest that Foxp3 degradation boosts anti-tumor immunity by alleviating Treg-mediated immunosuppression." (PMID 40470210, 2025). "This inhibitory effect is well documented in Tregs and certain tumor cells, where the Foxp3–NF-κB axis plays a critical role in Treg differentiation and function." (PMID 40989817, 2025).
tumor (continued). "Foxp3+ Tregs are increased in patient blood and decline postoperatively, implicating them in tumor development." (PMID 41181112, 2025). "The mechanistic contradictions in FOXP3’s role across cancer types likely stem from its interaction with cancer-specific signaling pathways and the distinct cellular context of each tumor." (PMID 39883234, 2025). "To explore this, we analyzed the association between CMTM4 expression and CD45+ tumor‐infiltrating leukocytes (including CD68+ macrophages, CD19+ B cells, CD8+ T cells, and FOXP3+ regulatory T cells [Tregs]) in the TCGA‐OC cohort." (PMID 40433989, 2025). "Tumor-derived metabolites, such as lactate and adenosine, sustain Treg suppressive function and promote FoxP3 stability, representing a key metabolic axis that supports their persistence in hypoxic conditions." (PMID 41394821, 2025). "In a pancreatic cancer animal model, the deletion of α-SMA + CAFs led to an increase in CD4 + Foxp3 + regulatory T cells within the tumours, resulting in accelerated tumour growth." (PMID 39780187, 2025). "Taken together, these data suggest that NLRP3 promotes Foxp3 expression in Th17 cells and facilitates their conversion into Tregs, thereby promoting tumor growth." (PMID 40195474, 2025). "The associations between mTLS and tumor infiltrating CD8+, PD-1+ and FOXP3+ TILs have partly been described previously in HGSC, but our findings suggest an association only in pMets." (PMID 39751944, 2025). "In B-cell lymphoma, elevated IL-10 and TGF-β from FOXP3+ Tregs enhance tumor progression and immune evasion." (PMID 41394821, 2025). "Further analysis confirmed the negative correlation between the numbers of AKT+CD4+ T cells and Foxp3+CD4+ T cells in the mouse tumor tissues." (PMID 39743020, 2025). "FOXP3 downregulation reduces tumor proliferation, invasion and immunosuppressive cytokine signalling, indicating a functional role in tumor progression and immune evasion." (PMID 41143064, 2025). "An increase in the ratio of CD8+ T-cells and Foxp3+ T-cells in tumour tissue further confirms the remodeling of the TME." (PMID 40160356, 2025). "We demonstrated that Gal1‐induced TAMs activated the CCL20 release via stimulating the PI3K/AKT/NF‐κB pathway, therefore triggering the recruitment of CCR6+Foxp3+ Tregs that impaired the anti‐tumor response of CD8+ T cells." (PMID 39853961, 2025). "Regarding cellular abundance, high-density CD8+ cells (mainly FoxP3- or PD-1-negative subsets) were indicative of better overall survival (OS), while several subsets of FoxP3+PD-L1+ in the tumor area suggested a poorer prognosis." (PMID 40422521, 2025). "Spatial transcriptomics revealed the enrichment of metastatic dissemination cells and FOXP3-related Treg cells at the tumor front in PT tissues." (PMID 40303346, 2025). "The RXR agonist MSU-42011 has been shown to reduce FOXP3+ Treg and increase activated cytotoxic T cells in several tumor murine models, including in MPNST." (PMID 40563570, 2025). "In OSCC, circRNA has_circ_0069313 has been found to promote tumor immune evasion through the miR-325-3p/Foxp3 axis, a mechanism impacting both OSCC cells and Tregs." (PMID 41221298, 2025). "Forkhead box protein P3 (FOXP3) is the master regulator of this population, and high expression levels of that molecule in tumor tissue indicate a highly immunosuppressive tumor milieu." (PMID 41428121, 2025). "The TIMER2.0′ Immune Association’ module analysis indicated a significant correlation between the expression of FOXP3, IL-10, and TGF-β1 and the abundance of tumor-infiltrating CD4+ CD25+ Foxp3+ Tregs, as inferred by the EPIC algorithm." (PMID 41438510, 2025).
tumor (continued). "While the observed correlations between FGFR2 and CD163+ or FOXP3+ immune cells are modest, their selective presence in ER+ tumours is noteworthy and warrants further investigation." (PMID 41018083, 2025). "In lung cancer, it was demonstrated that Treg cells were adjacent to CAFs and that infiltration of Foxp3+ Tregs and CAFs in the tumor stroma correlated with poor prognosis." (PMID 40244052, 2025). "FOXP3+ Treg cells are abundant at the differentiation terminal states of tumor-infiltrating CD4+ T cells." (PMID 41008548, 2025). "Relatlimab lead-in was characterized by clustering of CD8+ T and FOXP3+ T regulatory cells in the tumor microenvironment, enrichment in inhibitory receptor pathways and associated with worse PFS." (PMID 41282765, 2025). "This immunostimulatory effect was concomitant with a decrease in OX40+Foxp3+ Tregs in the tumor microenvironment." (PMID 41561762, 2025). "Accordingly, using an MC38 tumor model, we demonstrate that thiostrepton treatment reduces the number of intratumoral Foxp3+ Treg cells and prevents tumor growth." (PMID 40820379, 2025). "No significant changes in the population of neutrophils (CD45+CD3‐CD11b+Ly6G+), B cells (CD45+CD3‐CD19+) or Tregs (CD45+CD3+CD4+FOXP3+) were observed in the tumor TME following anti‐MARCO treatment or its combination with PD‐1 mAbs." (PMID 41117057, 2025). "Patients with a high infiltration level of CD68+ cells and Foxp3+ cells in tumor tissues are likely to benefit from neoadjuvant mono-immunotherapy." (PMID 39889711, 2025). "This suggests a role for Tregs in immune evasion, with higher FOXP3 expression contributing to a more immunosuppressive microenvironment that allows tumor progression." (PMID 41375087, 2025). "Comparative ligand-receptor analysis comparing CAF subsets with key T cell populations revealed that Fib_CD74+–CD4T_FOXP3+/CD8T_GNLY+ interactions were significantly enhanced in tumor samples." (PMID 40948762, 2025). "Accumulating evidence suggests that the presence of abundant CD4+FoxP3+ regulatory T cells (Tregs) within tumor tissue significantly contributes to the limited efficacy of ICIs in cancer treatment." (PMID 40038776, 2025). "FOXP3+ regulatory T-cells were significantly reduced in TGF-B2high tumours (p = 0.04), while higher tumoural TGF-B1 exhibited a trend towards increased FOXP3+ cells (p = 0.08)." (PMID 40826447, 2025). "Regulatory T cells (Tregs), characterized by FOXP3 expression, and immune checkpoint proteins such as PD-1 are known to suppress anti-tumor immune responses, allowing tumor progression." (PMID 41375087, 2025). "M-I treatment also downregulated the expression of PD1, PD-L1, and FoxP3 in the tumor, suggesting a strong candidate for immunotherapy in HNSCC." (PMID 41511327, 2025). "We performed multiplex immunofluorescence (mIF) using antibodies against CK, CD3, CD8, TCF1, and FOXP3 to assess diverse subsets of tumor-infiltrating lymphocytes (TILs) in 517 patients with stage III or high-risk stage II CRCs." (PMID 40519933, 2025). "In lung squamous cell carcinoma, a new subpopulation of CD3-/CD4+ cells, characterized by the high expression of FoxP3 and TNFα, has been identified, suggesting their proinflammatory role in the tumor immune microenvironment." (PMID 40292277, 2025). "We found that the proportion of tumor‐infiltrating CD4+CD25+Foxp3+ Tregs, especially the CCR6+ Treg subpopulation, was attenuated." (PMID 39853961, 2025). "An analysis of FOXP3 mRNA expression in tumor samples taken pre- and posttreatment showed a modest reduction in FOXP3 expression that was heterogeneous across patients treated with AZD8701." (PMID 39937271, 2025). "To solidify the mechanism of action of maraviroc in the LLC-bearing mice, we evaluated the tumor bed for infiltration of CD4+Foxp3+ T cells." (PMID 40553564, 2025). "Conversely, in aged OVX 67NR tumor-bearing mice, tacalcitol reduced Il17a expression, and calcitriol decreased Foxp3." (PMID 40894304, 2025).
tumor (continued). "Tregs with high Foxp3 expression have been confirmed to play a key role in inhibiting anti-tumor immunity." (PMID 40534854, 2025). "The detailed analysis of immune markers within the tumor microenvironment, particularly the expressions of FOXP3, PD-1, and CD32B, offers valuable insights into their potential as prognostic biomarkers and therapeutic targets." (PMID 41375087, 2025). "CD163+ and CD8+ cells were frequent in both tumor and stroma, while the FoxP3+ cell density was relatively low." (PMID 40422521, 2025). "APS have been shown to restore cytokine balance within the tumour microenvironment and downregulate FOXP3 mRNA expression, thereby attenuating the immunosuppressive activity of CD4+CD25+ Tregs." (PMID 40649307, 2025). "Tregs enhance tumor invasiveness through Foxp3-dependent epigenetic reprogramming, secrete IL-10 and TGF-β to inhibit CD8+ T cell cytotoxicity, and downregulate costimulatory molecules, hindering effective T cell activation." (PMID 40510347, 2025). "In tumor models of lung cancer, leukemia, and melanoma, TLR1/2 antagonists suppress the inhibitory function of Foxp3+ Tregs, enhance the cytotoxicity of tumor-specific CTLs, and lead to the depletion of tumor-infiltrating Treg cells." (PMID 41488647, 2025). "More importantly, animals treated with anti-PD-1 and TIGIT antibodies showed an increase in immune-infiltrated lymphocytes per tumour weight as well as the number of CD107a + CD8 + T cells and their ratio to CD4 + /Foxp3 + regulatory T cells within the tumour." (PMID 39939955, 2025). "Surgical specimens were analyzed based on CD3+, CD8+, and Foxp3+lymphocyte counts in the defined tumor area." (PMID 40274705, 2025). "An analogous population of Foxp3+ CD8 T cells have been described among tumor-infiltrating lymphocytes and in GVHD." (PMID 39824797, 2025). "Aberrant FOXP3 expression facilitates tumor immune evasion and supports oncogenic activation of pathways such as EGFR." (PMID 41301890, 2025). "For instance, scutellarin disrupts the TNF-TNFR2 interaction, reducing TNFR2 and Foxp3 expression, thereby lowering the proportion of tumor-infiltrating Tregs." (PMID 41458964, 2025). "In tumor immunosuppression, CAFs suppress host tumor immunity in vivo and in clinical practice; increased CD8+ tumor-infiltrating lymphocytes (TILs) and decreased forkhead box P3 (FoxP3)+ TILs are significantly correlated with CAFs and outcomes." (PMID 41154405, 2025). "Fourth, FoxP3+ regulatory T cells were increased in lymph nodes of both tumor-bearing and anti-mPD-1-treated mice compared to tumor-free controls, while their presence in tumor tissues was relatively low." (PMID 41208884, 2025). "In the tumor tissue of aged OVX 4T1 tumor-bearing mice, tacalcitol treatment increased the percentage of FoxP3+ cells." (PMID 40894304, 2025). "In ccRCC, FOXP3 appears to promote tumor progression not only by modulating the TME but also through direct effects on tumor cell proliferation and migration, as demonstrated in our functional experiments." (PMID 39883234, 2025). "Consistent with the impaired function of tumoral Treg cells subjected to Foxp3 protein degradation, we observed pronounced gene expression changes in tumor Treg cells in contrast to differentiated Treg cells in healthy mice." (PMID 40470210, 2025). "In mouse models, endothelial FASL limits T-cell infiltration, preferentially eliminating tumour-reactive CD8+ effector T-cells while sparing Tregs, skewing the CD8+/Foxp3+ T-cell ratio, and promoting immune tolerance and tumour progression." (PMID 40361472, 2025). "As an extension, IFN-γ and TNF-α neutralization resulted in a reduction of CD4+Foxp3+ Tregs in the LLC tumor bed compared with IgG-treated mice." (PMID 40553564, 2025). "In parallel, the FOXP3 transcription factor, classically known as a master regulator of regulatory T cells, has emerged as an important modulator of the tumor immune microenvironment." (PMID 41301890, 2025).
tumor (continued). "Among the most innovative strategies is the targeted degradation of FoxP3 using PROTACs (proteolysis targeting chimeras), which allows for precise modulation of the tumor microenvironment." (PMID 41394821, 2025). "A distinct subset of Tregs, known as T follicular regulatory (Tfr) cells, co-expresses FoxP3 and Bcl-6 and expands clonally upon recognizing tumor neoantigens." (PMID 40867165, 2025). "The ratio of intra- to extra-tumoral locations of immune cells was significantly higher in mutated tumours, especially for CD4, CD8 and FOXP3 lymphocytes." (PMID 40427006, 2025). "CD127lowCD25+Foxp3+ regulatory T cells (Tregs) were detected in 17 out of 20 (85%) tumor lesions, yet with low percentages." (PMID 40897471, 2025). "CRCs expressing SQSTM1/P62 have been reported to modulate immunosuppressive Foxp3 regulatory T cells inside the tumor microenvironment." (PMID 40066091, 2025). "The tumor-suppressive miR-34a, which is transcriptionally regulated by megakaryocytic leukemia 1 (MKL1), directly targets FOXP3 mRNA, thereby limiting Treg differentiation and its tumor-promoting effects." (PMID 41229433, 2025). "Studies show that CD4+CD25+Foxp3+ regulatory T cells (Tregs) are crucial in facilitating tumor immune evasion." (PMID 41438510, 2025). "IHC staining also demonstrated that LSD1 inhibition resulted in an augmented number of CD8+ CTLs, enhanced expression of PD‐L1 and a reduced number of FoxP3+ Treg cells in tumour tissues." (PMID 40356247, 2025). "With CRT-NP, decrease in tumor infiltration of Treg cells (CD4+ FOXP3+) cell was observed as well as increase in IFNγ expression on CD4+ T cells." (PMID 40386779, 2025). "Concurrently, in C57 BL/6 mice with AZD5582 application, the level of local CD8+ T-cell infiltration in the tumor was increased, while the level of Foxp3+ regulatory T-cell infiltration was significantly reduced." (PMID 39917292, 2025). "Tregs, characterized by Forkhead box P3 (Foxp3) expression, are key players in establishing an immunosuppressive tumor microenvironment." (PMID 41152975, 2025). "FOXP3’s dual role as both an immunosuppression regulator and a tumor suppressor in different cancers requires further investigation, especially given its stage-specific expression pattern." (PMID 40806346, 2025). "The percentage of FoxP3+ splenocytes decreased in aged 4T1 tumor-bearing mice treated with tacalcitol." (PMID 40894304, 2025). "PDAC: Significantly reduce the number of immunosuppressive Treg and FOXP3+ tumor cells, and increase the infiltration of antitumor CD8+ T cells." (PMID 40161377, 2025). "Specifically, we found that CD8+ T cells promoted homing of CD4+Foxp3+ Tregs to the tumor bed by increasing the levels of CCR5 chemokines in the tumor microenvironment in an IFN-γ– and TNF-α–dependent manner." (PMID 40553564, 2025). "According to clinical data, poor prognosis is strongly correlated with the simultaneous presence of both CAFs and Treg cells with high Foxp3 in the tumor stroma, indicating the possibility of crosstalk between them." (PMID 40805183, 2025). "The expression level of FOXP3 increased significantly in BC patients who had tumor grade 3 [FC: 16 (range: 1–230) compared to those with grade 2 [FC: 6.9 (range: 3–73), p = 0.005]." (PMID 40108523, 2025). "This review highlights how distinct T cell subsets, particularly CD8+ cytotoxic T lymphocytes and Foxp3+ regulatory T cells, exert opposing immunological influences that shape the tumor immune microenvironment." (PMID 40510347, 2025). "The mice with early Treg depletion had significantly higher tumoral Foxp3+ Tregs on day 23 compared with those with late Treg depletion even though they had continuous administration of DT, and the tumor sizes were the same." (PMID 40857404, 2025). "The TME consists of natural killer cells, CD8+ T cells, proinflammatory macrophages (M1), and DCs, which elicit antitumor immune responses, whereas the presence of MDSCs and FOXP3+ Treg counteracts tumor immunity." (PMID 41102383, 2025).